NUDT19 (nudix hydrolase 19)
Description:
Fatty acyl-coenzyme A (CoA) diphosphatase that hydrolyzes fatty acyl-CoA to yield acyl-4'-phosphopantetheine and adenosine 3',5'-bisphosphate (By similarity). Mediates the hydrolysis of a wide range of CoA esters, including choloyl-CoA and branched-chain fatty-acyl-CoA esters and at low substrate concentrations medium and long-chain fatty-acyl-CoA esters are the primary substrates (By similarity). Highest activity seen with medium-chain acyl-CoA esters and higher rates of activity seen with the unsaturated acyl-CoA esters compared with the saturated esters (By similarity). Exhibits decapping activity towards dpCoA-capped RNAs in vitro (By similarity).
Synonyms: RP2
Tractability: PROTAC: ubiquitination databases record sites on it; its protein half-life has been measured.
Gene: Protein-coding gene on chromosome 19 (32,691,821 to 32,713,792, forward strand). Ensembl gene ENSG00000213965.
Subcellular location: Peroxisome
Subcellular location (Human Protein Atlas): Cytosol; Vesicles
Pathways (Reactome):
Metabolism: Peroxisomal lipid metabolism
Protein localization: Peroxisomal protein import
Gene Ontology:
Molecular function: coenzyme A diphosphatase activity; magnesium ion binding; hydrolase activity, acting on acid anhydrides, in phosphorus-containing anhydrides
Biological process: butyryl-CoA catabolic process; coenzyme A catabolic process; fatty acid catabolic process; malonyl-CoA catabolic process; medium-chain fatty-acyl-CoA catabolic process; propionyl-CoA metabolic process; succinyl-CoA catabolic process
Cellular component: mitochondrion; cytosol; peroxisomal matrix; peroxisome
Genetic constraint (gnomAD): Loss-of-function variants: 28 observed, 16.84 expected, observed/expected ratio (o/e) 1.66, 90% interval 1.21 to 1.95. The synonymous counts are far from expectation, so gnomAD's model fits this gene poorly and the ratio says little. Missense variants: 700 observed, 426.54 expected, observed/expected ratio (o/e) 1.64, 90% interval 1.54 to 1.75. Synonymous variants: 304 observed, 187.5 expected, observed/expected ratio (o/e) 1.62, 90% interval 1.48 to 1.78.
Homologues: Orthologues: chimpanzee NUDT19 (99% identical), rabbit NUDT19 (70% identical), dog NUDT19 (68% identical), rat Nudt19 (64% identical), guinea pig NUDT19 (63% identical), mouse Nudt19 (63% identical), pig NUDT19 (55% identical), zebrafish nudt19 (39% identical), tropical clawed frog nudt19 (37% identical), Drosophila melanogaster CG10194 (30% identical), Drosophila melanogaster CG10195 (27% identical), Drosophila melanogaster CG18094 (26% identical), and 1 more.
Diseases named in the same sentence as NUDT19 in open-access papers:
NUDT19 is named in the same sentence as 10 diseases in open-access papers, as found by Europe PMC text mining. Sharing a sentence is not in itself a finding about the gene and the disease. The quoted sentences say what the papers report.
Alzheimer disease (2 papers, 2014 to 2023). A progressive, neurodegenerative disease characterized by loss of function and death of nerve cells in several areas of the brain leading to loss of cognitive function such as memory and language. "Nudt19, nudix (nucleoside diphosphate-linked moiety X)-type motif 19, is a potential biomarker of early stages of Alzheimer's disease and, along with multiple Nudix family hydrolases, may function in mRNA decapping and maintenance of mRNA stability." (PMID 25563673, 2014).
hepatocellular carcinoma (2 papers, 2023 to 2025). A malignant tumor that arises from hepatocytes. "In the hepatocellular carcinoma cell line, Nudt19 activated the mTORC1–P70S6K signaling pathway." (PMID 36830826, 2023).
Anxiety (1 paper, 2023). Intense feelings of nervousness, tension, or panic often arise in response to interpersonal stresses. "Recently, an analysis of the striatal proteome of depression-susceptible and anxiety-susceptible and -insusceptible rat cohorts detected Nudt19 among abnormally expressed proteins." (PMID 36830826, 2023).
Fibroadenoma (1 paper, 2020). A benign tumor of the breast characterized by the presence of stromal and epithelial elements. "We detected an increase in the expression of six proteins (NUDT19, FBN1, NONO, FLNA, SCPEP1, and galactosidase alpha) in fibroadenoma." (PMID 33194682, 2020).
tumor (2 papers, 2022 to 2025). "NUDT19 has been identified to promote the proliferation, migration, and EMT process of tumor via mTORC1/P70S6K signaling pathway." (PMID 36131793, 2022). "Overexpression of NUDT19 and the mTORC1 activator MYH1485 reverse the inhibitory effects of LINC00958 silencing on HCC proliferation, migration, and epithelial‐mesenchymal transition (EMT), and a large number of newly identified lncRNAs that are specifically expressed in tumor groups were found." (PMID 39630113, 2025).
cancer (1 paper, 2024). A tumor composed of atypical neoplastic, often pleomorphic cells that invade other tissues. "Notably, in the present study, ACSL1, ACSL5, and NUDT19 seemed to be cancer-promoting genes, as their upregulation was associated with poor survival." (PMID 38406287, 2024).
NUDT19 also shares sentences with these, for which no sentence is quoted: breast carcinoma (1 paper); depression (1); metabolic disorders (1); ovarian carcinoma (1).